KRAS (KRas proto-oncogene, GTPase)
Diseases named in the same sentence as KRAS in open-access papers (continued):
Sharing a sentence is not in itself a finding about the gene and the disease.
colorectal tumors (continued). "EGFR and KRAS: Approximately 30% to 50% of colorectal tumours are known to have a mutated (abnormal) KRAS, indicating that up to 50% of patients with CRC might respond to anti-EGFR antibody therapy, they only have a reasonable opportunity to derive clinical benefit from the therapy." (PMID 25361007, 2014). "In summary, our study presents a promising treatment strategy for patients with wild-type KRAS/NRAS/BRAF colorectal tumors." (PMID 39905540, 2025). "The primary colorectal tumors were predominantly left-sided (88%, n = 63) and KRAS wild-type (61%, n = 44)." (PMID 40696253, 2025). "Colorectal tumors arising through the serrated neoplasia pathway often carry BRAF mutations and only rarely KRAS mutations." (PMID 39039804, 2024). "MCLA-158, an LGR5 EGFR bispecific antibody, has therapeutic efficacy in preclinical models of various epithelial cancer types by inhibiting the growth of KRAS-mutant colorectal tumors, blocking metastasis initiation, and suppressing tumor expansion." (PMID 38481800, 2024). "Our nationwide study clearly demonstrates that BRAF V600E and KRAS G12C colorectal tumours show significantly detrimental clinicopathological features." (PMID 37240418, 2023). "To date, liquid biopsies have shown the selective pressure of anti-EGFR therapies in patients with RAS-wild-type * colorectal tumors, in that acquired resistance to EGFR blockade is often driven by the emergence of KRAS/NRAS mutations in plasma." (PMID 35159069, 2022). "MBD4-deficient polyps harbored somatic mutations in similar driver genes to sporadic colorectal tumors, although AMER1 mutations were more common and KRAS mutations less frequent." (PMID 35460607, 2022). "The expression of GSK-3β was elevated in colorectal tumor tissue in comparison to adjacent normal tissue almost in all patients both KRAS mutant and wild-type." (PMID 34955846, 2021). "Overall, 107 specimens from primary colorectal tumor were analyzed together with their corresponding specimens from CRLM, to analyze the concordance in KRAS mutation status." (PMID 33946899, 2021). "Aim of our study is to assess the incidence of KRAS discordance in a single-center series by comparing primary colorectal tumor specimens with the corresponding liver metastasis." (PMID 33946899, 2021). "In such patients, the KRAS mutation analysis was available only for the CRLM in 551 patients and both for the primary colorectal tumor and the corresponding CRLM, in 107 patients, who are the subjects of our study." (PMID 33946899, 2021). "Four somatic colorectal tumor markers were assessed individually and in combination, including BRAF mutation, KRAS mutation, CpG island methylator phenotype (CIMP), and microsatellite instability (MSI) status." (PMID 34377935, 2021). "The KRAS oncogene produces colorectal tumors resistant to anti-EGFR therapies by activating the Ras-Raf-MAPK pathway downstream of EGFR." (PMID 32054005, 2020). "Thirty-eight (84.4%) of KRAS mutant colorectal tumors were left-sided while 7 (15.6%) were right-sided." (PMID 32079384, 2020). "Especially, KRAS mutant fragments were detected in the blood of patients with KRAS-mutant colorectal tumors, with high specificity (99.2%) and sensitivity (87.2%)." (PMID 31781302, 2019). "When we analyzed a series of invasive colorectal tumors (n = 374), we again found that elevated SMOC1 methylation was associated with KRAS mutation and CIMP-low." (PMID 29435136, 2018).
colorectal tumors (continued). "While a subset of colorectal tumors, apparently wild-type for KRAS, are sensitive to EGFR inhibition, they almost always develop secondary resistance after an initial response." (PMID 30127519, 2018). "Patients with a colorectal tumor bearing WT KRAS, which often expresses WT EGFR, do benefit from cetuximab therapy." (PMID 29685162, 2018). "We xenografted SW620 (KRAS p.G12V) colorectal tumour cells into immunocompromised mice and once tumours had established, we treated animals with AZD5438." (PMID 26881434, 2016). "Conversely, the coexistence of mutations in KRAS and PIK3CA has been described in a significant percentage of colorectal tumors, confirming the parallel activation of ERK/MAPK and PI3K/AKT signaling convergent pathways." (PMID 26968814, 2016). "Studies characterizing patients with PIK3CA-mutated CRC have suggested that tumors exhibiting these mutations are more likely to be located in the proximal colon, and to exhibit KRAS mutations than PIK3CA-wildtype colorectal tumors." (PMID 26337942, 2015). "The molecular characteristics in this cohort demonstrate the general distribution within colorectal tumors and mutual exclusivity of the oncogenes KRAS and BRAF." (PMID 25742883, 2015). "A rabbit anti-human KRAS polyclonal antibody was tested on 33 FFPE colorectal tumor samples with known KRAS status." (PMID 25983749, 2015). "In this study, we aim to elucidate the frequency of KRAS mutation and BRAF mutation in polypoid, flat and depressed colorectal neoplasms and compare these morphological counterparts each other." (PMID 25551625, 2014). "Out of the 100 patients presenting left-sided colorectal tumors, 68 tumors presented KRAS codon 12/13 wild-type tumors, and 32 tumors had KRAS codon 12/13 mutations." (PMID 24816724, 2014). "Within this context, the KRAS gene bears significant predictive value relative to the use of anti-EGFR therapies in colorectal neoplasms." (PMID 29147353, 2013). "Our previous results have indicated that oncogenic KRAS in colorectal tumour cells sensitises these cells to chemotherapy." (PMID 20354524, 2010). "In contrast, we along with others have previously shown that oncogenic KRAS promotes apoptosis of human colorectal tumour cells exposed to either 5-FU or oxaliplatin." (PMID 20354524, 2010). "In colorectal tumours, increased vimentin expression correlates with the presence of oncogenic KRAS and with nuclear beta-catenin." (PMID 19367286, 2009). "Using genetically engineered mouse models, patient-derived organoids and xenografts, as well as clinical specimens, we discover that colorectal tumors surviving combined KRAS and EGFR inhibition acquire a Paneth-like cell state-a secretory lineage typically confined to the intestinal crypt." (PMID 41237766, 2025). "KRAS mutations account for 40% of all genetic mutations in colorectal tumors, however, due to the small number of patients, there were no previous reports of mutant KRAS gene in CASC." (PMID 38229035, 2024).
colorectal tumors (continued). "Finally, SComatic also identified subclonal deleterious mutations in cancer driver genes frequently mutated in the cancer types analyzed, such as MLH1, TGFBR2 and KRAS in colorectal tumors, indicating that SComatic can discover subclonal driver mutations." (PMID 37414936, 2024). "In addition, the combination of NCB-0846 and ABT-263 (BCL-X) inhibitor also showed synergistic inhibition of colorectal tumors in the KRAS mutant xenograft model." (PMID 38226156, 2024). "KRAS and BRAF mutations are generally mutually exclusive in colorectal tumors." (PMID 38786305, 2024). "For example, it has been reported that among non-hypermutated colorectal tumors, KRAS was mutated in only about 43% of patient samples, indicating the importance of a variety of evolutionary pathways." (PMID 35416770, 2022). "Finally, we utilized the single-cell RNA-seq data to compare the difference of TME cell-infiltrating landscape based on bulk WES-identified KRAS-WT and KRAS-Mut colorectal tumors." (PMID 35836817, 2022). "KRAS mutational status was determined on either the resected CRLM or the primary tumor, with the caveat that primary colorectal tumors may differ from their metastases with regard to the mutational status." (PMID 35159066, 2022). "In contrast, KRAS gene abnormalities are observed at the same frequency as in colorectal tumors." (PMID 35566730, 2022). "Finally, a total of 55539 single cells derived from 16 KRAS-WT and 13 KRAS-Mut colorectal tumors were obtained and analyzed by Seurat 4.0." (PMID 35836817, 2022). "This combination therapy failed todelay tumour growth and did not lead to an increase in thesurvival of tumour-bearing mice.It has previously been shown that MEK inhibition enhances anti-tumour immunityand synergises with anti-PD-L1 in KRAS-mutant CT26 colorectal tumours." (PMID 35930804, 2022). "Indeed, knocking down Smurf2 reduces KRAS abundance, impairs clonogenic survival and prolongs tumor latency in mutant KRAS-driven lung and colorectal tumor models." (PMID 33562401, 2021). "Our study showed that discordance of KRAS mutation status between primary colorectal tumor and the corresponding CRLM does not represent a rare event." (PMID 33946899, 2021). "This includes the scenario of EGFR inhibitors for KRAS wild-type colorectal tumors." (PMID 31990579, 2020). "The major aim of this study was to evaluate the performance of anti-BRAF V600E (VE1) antibody in colorectal tumors with and without KRAS mutation." (PMID 29127628, 2019). "Moreover, the treatment of patients with mutant KRAS colorectal tumors with EGFR inhibitors seemed to aggravate disease progression." (PMID 30858928, 2019). "Furthermore, it is a remarkable fact that colorectal tumor is a disease due to different genetic and epigenetic alterations, such as microsatellite instability and activation of oncogenes including KRAS and BRAF." (PMID 30636375, 2019). "Moreover, the co-occurrence of KRAS and BRAF mutations in the same colorectal tumor has been reported in few studies." (PMID 28580315, 2017). "Arbitrary selected 75 colorectal tumors were analyzed for BRAF, KRAS, and NRAS gene mutations." (PMID 28460459, 2017). "For example, it has been shown that colorectal tumors that are wild type for KRAS are often sensitive to targeted epidermal growth factor receptor (EGFR) blockade; however, KRAS mutations become detectable at the time of acquired resistance to this targeted drug." (PMID 26912072, 2016).
colorectal tumors (continued). "For example, the proto-oncogene KRAS is found mutated in ~42 % of colorectal tumors but in less than 1 % of breast tumors; whereas amplification of ERBB2 is found in ~13 % of breast tumors but in only ~3 % of colorectal tumors." (PMID 26429708, 2015). "Point mutations in KRAS gene were found in 41.2% (7 out of 17 tumor samples) of colorectal tumors from patients with no identified MMR mutations." (PMID 26437257, 2015). "Similarly, KRAS G12D mutations and MAPK1 (MEK) and MET amplification are published biomarkers for colorectal tumor sensitivity to both MEK and MET inhibitors." (PMID 24621249, 2014). "Colorectal tumors with wild-type KRAS are often sensitive to EGFR blockade." (PMID 24304820, 2013). "Indeed, better response rates to bevacizumab can be observed in KRAS wt colorectal tumors when compared to KRAS mutant." (PMID 23506169, 2013). "Recently, authors that were investigating the relationship between KRAS mutations and prognoses for CRC cases have observed that KRAS mutations lead to the higher turnover of colorectal tumour cells, which stimulates both mitosis and apoptosis and is related to a poor survival of CRC." (PMID 24106912, 2013). "In a significant fraction of colorectal tumors, Wnt and KRAS pathway alterations coexist." (PMID 23227266, 2012). "Patients with a colorectal tumor bearing mutated KRAS did not benefit from cetuximab, whereas patients with a tumor bearing wild-type KRAS did." (PMID 20565817, 2010). "Advances in the understanding of colorectal tumor biology and oncogenic signaling have enabled the development of biomarker-guided therapies targeting alterations in EGFR, BRAFV600E, KRAS mutations and HER2 amplifications, improving outcomes in selected patient populations." (PMID 42074578, 2026). "However, patients with colorectal tumors harboring KRAS mutations do not benefit from anti-EGFR treatment." (PMID 39123483, 2024). "For example, activating mutations in the Kirsten Rat Sarcoma Viral Oncogene Homolog (KRAS) or V-Raf Murine Sarcoma Viral Oncogene Homolog B (BRAF) oncogenes confer proliferative characteristics and are found in 30% or 15% of sporadic colorectal tumours, respectively." (PMID 35326545, 2022). "Our results highlight that the only evaluation of KRAS mutation status in primary colorectal tumor may be not always adequate to predict response to anti-EGFR therapy of the corresponding CRLM." (PMID 33946899, 2021). "Somatic G → T mutations in the APC and KRAS genes are frequently observed in such colorectal tumors in MAP patients, and even in non-MAP patients, reduced MUTYH expression is associated with an increased number of somatic G → T mutations in prostate adenocarcinoma." (PMID 29098062, 2017). "Thus, new biomarkers must be identified to further characterize BRAF or KRAS mutation-negative colorectal tumours." (PMID 27248823, 2016). "Although activating mutations in KRAS alone do not reliably predict the response of colorectal tumours to chemotherapy, these findings do suggest that the acquisition of KRAS mutations may be associated with an increased propensity to undergo apoptosis." (PMID 20354524, 2010). "A previous study that evaluated KRAS status in primary colorectal tumors and non-matched liver and lung metastases showed concordant results with our study and revealed a higher incidence of KRAS mutations in lung metastases than in liver metastases (57% vs 50%)." (PMID 20020061, 2009). "When comparing the frequency of KRAS mutations found in our series of colorectal polyps with those observed within the MSS and MSI subsets of CRC, the frequency of KRAS mutations found in polyps is not statistically different from the frequency observed in MSI and MSS colorectal tumours." (PMID 18782444, 2008). "Recent data from our group evaluating 24 patients with CRC shown that most colorectal tumors were microsatellite stable (98%), CIMP-low (92%), and had wild-type KRAS (69%) and BRAF (91%)." (PMID 35648382, 2023).
colorectal tumors (continued). "However, it has been showed that resistance to anti-EGFR therapy may also occur among patients without KRAS mutation in colorectal tumors (KRAS wild-type)." (PMID 33946899, 2021). "We sought to assess the role of oncogenic KRAS in the regulation of MYC expression in cell lines derived from lung and colorectal tumors and the effects of MYC on cellular cytotoxicity and drug sensitivity according to KRAS mutation status." (PMID 28152508, 2017). "Thus, our studies demonstrated that SLC25A22 is an essential regulator of the metabolic system of KRAS-mutant colorectal tumor and its overexpression promotes tumor cell growth, which could provide more insights into KRAS-mutant CRC therapy with treatment of polyamine-inhibitor." (PMID 29254168, 2017). "The same experimental strategy was then applied to an independent PDX that was also derived from a quadruple wild-type (KRAS, NRAS, BRAF and PIK3CA) colorectal tumour and was sensitive to EGFR blockade." (PMID 26392303, 2015). "This was derived from an individual carrying a quadruple wild-type (KRAS, NRAS, BRAF and PIK3CA) colorectal tumour, and thus recapitulates the molecular profile of patients sensitive to anti-EGFR antibodies." (PMID 26392303, 2015). "Colorectal tumors of FAP and non-polyposis patients showed a similar frequency of mutations (APC, 76% and 75%; KRAS, 32% and 25%)." (PMID 41488735, 2025). "The mutant KRAS results in immune evasion by recruiting myeloid-derived suppressor cell (MDSC) and impairing CD8+ T cell activity via inhibition of IRF2 and activation of CXCL3 production in mouse models with colorectal tumors." (PMID 36172359, 2022). "On the other hand, concomitant KRAS and BRAF-mutated colorectal tumors are relatively rare, so that the routine analysis of BRAF mutations in tumors with the KRAS mutations is not recommended." (PMID 28580315, 2017). "Therefore this study provides for the first time, a comparative study of BRAF, KRAS and HRAS oncogenes regarding their differential regulation of autophagic markers and related properties in colorectal tumor cells." (PMID 26802026, 2016). "The trial is designed to include an enriched population of patients with KRAS and NRAS wild-type rectal cancer due to evidence of lack of benefit from anti-EGFR strategies in KRAS or NRAS mutated colorectal tumors." (PMID 27655166, 2016). "However, several reports showed that mutations in genes involved in the Ras-Raf-MAPK pathway, like KRAS and BRAF, are important biomarkers for colorectal tumor patient response to anti-EGFR mAbs." (PMID 23207070, 2012). "Both our results and those obtained by Whitehall show that a significant number of samples from colorectal tumor and NSCLC contain mixtures of KRAS wild-type and KRAS mutant cells, and that in many cases the percentage of mutant cells is below the threshold that can be detected by direct sequencing." (PMID 22995035, 2012). "One promising example is the KRAS G12C inhibitor sotorasib, which covalently binds the mutant cysteine in a hidden pocket of KRAS, traps the protein in its inactive GDP-bound state, and effectively quenches aberrant MAPK signaling in G12C-mutant colorectal tumors." (PMID 41229498, 2025). "We cannot rule out that additional mutated genes, such as KRAS, could interact with the ME1 function, since mutations in the latter were shown to increase ME1 mRNA levels in colorectal tumors." (PMID 36612292, 2022). "However, on a positive note, we did observe that these tumors, unlike KRAS mutant colorectal tumors, are vulnerable towards combinatorial targeting strategies against the RAS-MAPK pathway." (PMID 30858928, 2019).